INS (insulin)
Diseases named in the same sentence as INS in open-access papers (continued):
Sharing a sentence is not in itself a finding about the gene and the disease.
Insulin resistance (continued). "Increased expression of PTP1B in insulin-sensitive tissues is a marker of insulin resistance, while decreased expression enhances insulin sensitivity, thereby improving glucose uptake and insulin signaling." (PMID 30875760, 2019). "In obesity, adipose tissue macrophages are polarized into pro-inflammatory M1 macrophages and secrete many pro-inflammatory cytokines capable of impairing insulin signaling, therefore promoting the progression of insulin resistance." (PMID 32063863, 2019). "Insulin resistance increases the prevalence of T2D sixfold as marginal insulin secretion becomes inadequate insulin secretion." (PMID 31776781, 2019). "IL-1β is an important proinflammatory cytokine that drives the pathogenesis of liver inflammation, hepatic steatosis, liver fibrosis, and insulin resistance by impairing insulin signaling in the liver, muscle, and adipose tissue." (PMID 31485221, 2019). "Circulating amino acids have been shown to be predictive of the development of insulin resistance, and promote insulin resistance via inhibiting insulin signalling." (PMID 31065046, 2019). "A linear regression model was used to test the relationship between fat intake and body composition, insulin resistance, and insulin secretion." (PMID 30871233, 2019). "It is well-known that obesity is commonly accompanied by insulin resistance, and for this reason serum glucose and insulin levels were also measured, and the Homeostatic Model Assessment for Insulin Resistance (HOMA-IR) was calculated." (PMID 31861663, 2019). "Palmitate plays a critical role in the initiation and development of insulin resistance as exposure of C2C12 cells to palmitate suppressed insulin-stimulated Akt1 phosphorylation and glucose uptake." (PMID 31266232, 2019). "Mice lacking of SIRT4 had abnormal leucine metabolism, which resulted in chronic increase of insulin secretion and accelerated senescence-induced insulin resistance." (PMID 31447696, 2019). "Inhibition of this enzyme suppresses postprandial hyperglycaemia, and upregulation of pPI3K improves insulin signalling mechanisms, thus alleviating insulin resistance." (PMID 31878222, 2019). "Our findings are consistent with previous studies that demonstrated impaired β-cell function, high insulin resistance, and decreased insulin sensitivity only in patients with abnormal glucose tolerance, but β-cell function was preserved in patients with NGT." (PMID 31736874, 2019). "Such modulators are controlled by insulin metabolism and cytokines and, while anorexics display inflammatory predominance, obese patients predominantly display insulin resistance." (PMID 31191339, 2019). "These G6PD-deficient mice exhibit glucose and insulin tolerance as well as reduced insulin signaling, suggesting that G6PD deficiency is associated with an improvement in insulin resistance." (PMID 31500396, 2019). "In contrast to chronic insulin exposure that induces neuronal insulin resistance, the adverse factor in excitotoxicity, the short-term insulin exposure in our experiments was shown to be a protective treatment against excitotoxicity." (PMID 31611766, 2019). "There is also data indicating that metformin reverses insulin resistance and decreases serum insulin concentration during the first 6 to 14 days of treatment, however, this effect diminishes by 220 days." (PMID 30678275, 2019). "Circulating FGF21 levels are elevated in subjects with obesity, T2D, and MetS, and positively correlate with triglycerides, fasting insulin, and insulin resistance." (PMID 31736870, 2019). "Resveratrol is a natural phytoalexin that exists widely in many plants and can increase insulin sensitivity and improve insulin resistance." (PMID 31340585, 2019). "•The data present in this data article show that Ide knockout mice present increased glucose and insulin levels at 18 weeks of age, as well as increased insulin resistance." (PMID 31198829, 2019).
Insulin resistance (continued). "So the main roles of insulin in the brain, regulation of body homeostasis and balancing of nutrient intake and energy expenditure are all altered in insulin resistance." (PMID 31143098, 2019). "Relatively elevated concentrations of insulin induced by insulin resistance boosts hepatic IGF-I synthesis and increases circulating IGF-I activity, which then also binds to IR, IGF-1R, and IR/IGF-1R to enhance the signaling." (PMID 31847392, 2019). "Insulin resistance is clinically defined as a condition of impaired insulin sensitivity to glucose uptake and/or utilization." (PMID 31330848, 2019). "These animals were obtained by repeated selective breeding of glucose intolerant Wistar rats exhibiting peripheral insulin resistance and impaired insulin secretion." (PMID 30858895, 2019). "It has been shown that increased concentrations of IL-1β and IL-6 contribute to the weakening of insulin signaling, presumably leading to insulin resistance." (PMID 31707362, 2019). "The characteristics of T2DM are mainly insulin resistance and insufficient insulin secretion, which result in high levels of blood glucose." (PMID 31396083, 2019). "In adipocytes and in VSMCs, aldosterone blocks insulin signaling, contributing to insulin resistance." (PMID 31447681, 2019). "Patients administered genistein showed lower fasting serum glucose levels, insulin levels, and homeostasis model assessment for insulin resistance (HOMA-IR), which contributed to the lowered fat deposition in the blood vessels and the heart." (PMID 31671813, 2019). "A functional variation (SNP rs10152450 and haplotype GGAAT) in the FEM1B gene increases insulin secretion and insulin resistance in mice, and the result is ovarian hyperandrogenism that occurs at the time of puberty in polycystic ovary syndrome (PCOS)." (PMID 31083386, 2019). "Administration of C57BL/KsJ-db/db mice with curcumin (0.02% wt/wt) for 6 weeks resulted in significantly reduced serum glucose and HbA1c levels and an increased serum insulin level and homeostatic model assessment of insulin resistance (HOMA-IR)." (PMID 31881654, 2019). "To understand the effects of DS-EA on glucose metabolism and insulin resistance in db/db mice, we measured fasting blood glucose levels, glucose tolerance, and insulin levels." (PMID 30841605, 2019). "A meta-analysis of 102 randomised controlled feeding trials with 4,200 subjects has reported that PUFA had the most beneficial effects in improving glycaemia, insulin resistance, and insulin secretion in comparison to dietary carbohydrate, SFA, and MUFA." (PMID 31007954, 2019). "Our findings clearly demonstrated that HbA1c as well as leptin, adiponectin, and insulin were strongly related to both glucose tolerance and insulin resistance." (PMID 31379415, 2019). "Another relevant finding of the present work is the effect of oleacein on the expression of Adiponectin, an adipocyte-derived hormone with insulin-sensitizing activity, which is commonly downregulated in obesity and insulin resistance." (PMID 31394876, 2019). "It involves the 10% of world’s population and it is characterized by hyperglycemia due to a defective insulin secretion or insulin resistance." (PMID 31835864, 2019). "Many mechanisms have been proposed to link insulin resistance or hyperinsulinaemia to hypertension, including stimulation of the sympathetic nervous system, sodium absorption by hyperinsulinaemia, and impaired insulin stimulation of vasodilation." (PMID 30978266, 2019). "The regulation of insulin resistance in WAT by PPARγ is accompanied by alterations of several components of insulin signaling and is often co-regulated." (PMID 31614949, 2019). "In the course of obesity, the increased lipid accumulation induces a systemic chronic inflammation that promotes an abnormal cellular response to insulin, leading to insulin resistance and type 2 diabetes (T2D)." (PMID 31888081, 2019).
Insulin resistance (continued). "Insulin resistance reduces the sensitivity of insulin to increase triglyceride hoarding and body weight." (PMID 31666589, 2019). "Since fasting insulin in children has been acknowledged as an index of insulin resistance in epidemiological studies by an expert panel, it seems reasonable to also employ it as a surrogate marker in neonates." (PMID 31031804, 2019). "Insulin resistance is a state with a normal or higher insulin level but lower effect on the glucose uptake." (PMID 31071176, 2019). "Insulin resistance is a pathophysiological condition in which cells fail to respond to normal insulin signals to store glucose in the tissues." (PMID 31246177, 2019). "Accordingly, Rgs16 reconstitution substantially exacerbated insulin resistance in db/db mice as defined by serum insulin, glucose, and HOMA2-IR." (PMID 30962478, 2019). "TZDs decrease both fasting and postprandial hyperglycemia by decreasing insulin resistance and allowing endogenous insulin to be more effective." (PMID 31776781, 2019). "It has been confirmed that patients that have reached the IGR stage already exhibit insulin resistance and insulin secretion defects." (PMID 31043161, 2019). "Fasting glycemia, insulin levels, homeostasis model assessment for insulin resistance (HOMA-IR), lipid profile, gene expression, and lipid content of liver and adipose tissues were analyzed after three months of treatment." (PMID 31888081, 2019). "Elevated serum uric acid (SUA) has a positive correlation with insulin secretion and insulin resistance indexes." (PMID 30941277, 2019). "MOTS‐c levels are correlated with markers of insulin resistance and obesity including BMI, waist circumference, waist‐to‐hip ratio, fasting insulin level, HOMA‐IR, HbA1c." (PMID 31293078, 2019). "To determine the effects of insulin resistance on the skin, we inhibited insulin signaling in 3D-keratinocytes and examined the expression of skin function-related molecules whose levels in mice were influenced by the HFD." (PMID 31581253, 2019). "Measures of insulin resistance were calculated using both fasting and postprandial glucose and insulin concentrations." (PMID 31569345, 2019). "Our data suggest that there is increased circulating insulin and insulin resistance under HFD feeding." (PMID 31853220, 2019). "Although the exact relationship between MetS and skin diseases is still unclear, insulin signaling, insulin resistance, and chronic inflammation are believed to contribute." (PMID 31824416, 2019). "While acute administration can improve insulin sensitivity in humans, chronic unregulated activation of Ang II pathways produces insulin resistance, glucose intolerance, and oxidative stress." (PMID 31262355, 2019). "While type 1 diabetes (T1D) is caused by autoimmune destruction of the insulin-producing beta cells of the pancreas, type 2 diabetes (T2D) results from a combination of insulin resistance and beta cell insulin secretory defect." (PMID 31685799, 2019). "Insulin resistance implies impaired insulin-induced glucose uptake and metabolism in adipocytes and skeletal muscle, and impaired suppression of hepatic glucose production." (PMID 31178685, 2019). "The pattern of insulin requirements in pregnancy varies between women with type 1 and type 2 diabetes, suggesting a differential effect of pregnancy-mediated insulin resistance." (PMID 31828161, 2019). "This peripheral insulin resistance induces pancreatic β cells to secrete more insulin, leading to hyperinsulinemia, which often leads to β cell depletion and sustained hyperglycemia in T2D." (PMID 31141900, 2019). "Recently, studies reported that dietary polyphenols can reduce or prevent insulin resistance and enhance insulin sensitivity." (PMID 30717198, 2019). "The central role of inflammation in the development of insulin resistance is further corroborated by studies that show that anti-inflammatory drugs are able to improve insulin sensitivity and related complications." (PMID 31438590, 2019).
Insulin resistance (continued). "Products of intracellular cytokine activation decrease insulin sensitivity of the receptors, thus triggering the development of insulin resistance." (PMID 30881343, 2019). "These cells are consequently more prone to developing insulin resistance, and this explains the impaired inhibition of gluconeogenesis in an insulin resistant organism." (PMID 31010049, 2019). "It is well known that TNF-α promotes insulin resistance by inhibiting IRS1 (insulin receptor substrate 1) and IL-1β causes apoptosis in β-pancreatic cells, thereby diminishing insulin production." (PMID 31430882, 2019). "In T2D, insulin resistance (i.e., the inability of cells to respond to insulin to take up glucose) leads to excessive insulin production by beta cells, resulting in their exhaustion and eventual death." (PMID 31683538, 2019). "The hepatic insulin resistance likely results from impaired CEACAM1-dependent hepatic insulin clearance pathways and resultant chronic hyperinsulinemia." (PMID 31266142, 2019). "E2 has been reported to enhance insulin sensitivity and ameliorate insulin resistance in lots of experiments." (PMID 31849684, 2019). "Due to the central role of GLUT4 in insulin-dependent glucose uptake, impaired GLUT4 translocation can cause insulin resistance." (PMID 32133058, 2019). "Metabolic diseases such as obesity and coronary disorders can be the consequence of insulin resistance, i.e., the inability of insulin to drive glucose into muscle and other tissues, which can be caused by excessive body fat deposition." (PMID 31354792, 2019). "Despite the well-established role of impaired feedback in the inhibition of insulin secretion in hyperinsulinemia and insulin resistance, multiple central and peripheral endocrine and inflammatory pathways are also disturbed." (PMID 31781037, 2019). "After T2DM mice reconstructed their microbiota through the feces received from normal mice, fasting insulin levels were decreased and insulin resistance was improved." (PMID 32010641, 2019). "In agreement with these, it has been shown that diabetic rats had significantly decreased body weight but increased fasting blood glucose, oral glucose tolerance, fasting serum insulin, and insulin resistance index as well as lipid levels." (PMID 31019978, 2019). "Inhibition of tyrosine phosphatases, such as PTP1B and TCPTP, was found to stimulate insulin signaling and glucose uptake and to ameliorate insulin resistance in diabetic mice." (PMID 31234331, 2019). "The enhanced glucose clearance from the circulation following intraperitoneal injection of glucose or insulin further corroborates our assumption that intestinal Ces2c overexpression protects from HFD‐induced insulin resistance." (PMID 30766961, 2019). "The decreased 11 β HSD1 was attributed to insulin.Insulin directly inhibits 11 β HSD1 activity in liver.Insulin resistance would similarly increase 11 β HSD 1 activity." (PMID 30678666, 2019). "On the contrary, these adverse effects of acute eccentric exercise on insulin resistance subsided after chronic exercise, showing decreased resting levels of insulin, glucose and HOMA." (PMID 31265450, 2019). "Because of the prevalence and pathologies arising from insulin resistance, numerous pharmacological therapies are commonly utilized to improve insulin sensitivity." (PMID 31485454, 2019). "In the current study, we provided evidence that AHG treatment significantly alleviated fasting blood glucose and improved insulin resistance by suppressing gluconeogenesis in HFD-fed insulin resistant mice." (PMID 31861309, 2019). "Insulin resistance is the decreased biological response to a given insulin dose, be it endogenous or exogenous, in the target tissue (liver, muscle, or adipose tissue)." (PMID 31828161, 2019).
Insulin resistance (continued). "Some studies, conducted on obese or diabetic rats, showed that taurine supplementation ameliorated glucose tolerance and insulin sensitivity along with decreasing insulin resistance, hyperinsulinemia, and hyperglycemia." (PMID 30862074, 2019). "As insulin sensitizers, Ros mainly acts on restoration of insulin secretion and reduction of insulin resistance." (PMID 30651718, 2019). "The aim of this study was to compare glucose tolerance between KTRs and healthy subjects using the OGTT, and we assessed the prevalence of glucose intolerance including IFG and/or IGT as well as insulin secretion and insulin resistance using the HOMA." (PMID 31252561, 2019). "A single injection of vitamin D significantly decreased serum insulin levelsand insulin resistance among patients with polycystic ovary syndrome." (PMID 31091067, 2019). "Vitamin D is another constituent of dairy with several possible effects on insulin resistance through pancreatic beta-cell function, insulin sensitivity, and inflammation." (PMID 31533272, 2019). "A study found that fasting blood glucose, blood insulin, and insulin resistance index were significantly increased as the urinary MuA increased." (PMID 30823556, 2019). "Consumption of glycogen reduces the secretion of insulin, promotes the corresponding receptor binding of insulin in the blood circulation to improve insulin resistance, and enhances glucose metabolism." (PMID 31341475, 2019). "We detected an emerging insulin resistance with testosterone treatment elevating glucose levels and vitamin D deficiency elevating insulin levels and leading to a higher computed HOMA-IR (Homeostatic Model of Insulin Resistance) value following OGTT." (PMID 31509973, 2019). "Insulin resistance, characterized by a dampened response to insulin signals and decreased uptake and/or utilization of glucose in the target tissue, is a major cause of type 2 diabetes." (PMID 31126054, 2019). "Instead, we calculated HOMA-IR and Matsuda ISI based on both fasting and postprandial glucose and insulin concentrations, which are valid surrogate measures for insulin resistance in large population-based studies." (PMID 31569345, 2019). "T2DM is a type of metabolic disease that is characterized mainly by a reduction in insulin sensitivity (insulin resistance), which in turn decreases insulin-stimulated uptake of blood glucose." (PMID 30875966, 2019). "The fasting serum insulin and glucose levels and theinsulin sensitivity and homeostasis model assessment of insulin resistance did notshow a significant difference by the end of the study." (PMID 31091067, 2019). "Insulin resistance is a condition characterized by reduced responsiveness of target tissues to normal circulating levels of insulin." (PMID 30871083, 2019). "For all subjects, Serum Adiponectin and Insulin Resistance parameters (Fasting serum Insulin, Fasting serum Glucose, HOMA IR) were measured." (PMID 31244307, 2019). "Recombinant resistin triggered systemic insulin resistance in mice and decreased insulin-mediated glucose uptake in adipocytes." (PMID 31208019, 2019). "In people with similar total fat masses, subcutaneous fat mass is negatively correlated with atherogenic metabolic risk factors and visceral fat deposition initiates a dysfunctional state in the insulin-sensitive tissues leading to insulin resistance." (PMID 31719833, 2019). "Insulin resistance and high insulin levels directly and indirectly stimulate ovarian theca cells to secrete androgens, and these result in an increase of androgen levels." (PMID 30863446, 2019). "After probiotic supplementation in our study, the levels of fasting plasma glucose, insulin, and homeostasis model assessment of insulin resistance were found to be consistent with the literature." (PMID 31284705, 2019). "Improved insulin sensitivity upon treatment with herbal medicine provides considerable prospects for treating insulin resistance." (PMID 31258478, 2019).